IL1B (interleukin 1 beta)
Diseases named in the same sentence as IL1B in open-access papers (continued):
Sharing a sentence is not in itself a finding about the gene and the disease.
chronic fatigue syndrome (9 papers, 2015 to 2025). "Further supporting this notion, the IL1 receptor antagonist, which potently inhibits IL1β/IL1r1 signaling, was recently found to be ineffective at reducing pain in the treatment of women with chronic fatigue syndrome, which has also been linked to insufficient peripheral perfusion." (PMID 29298725, 2018). "In the murine model of chronic fatigue syndrome, the combination of AM and AS was found to increase body weight and endurance capacity and to decrease mRNA levels of IL-1β, TNF-α, NF-κB, and p38MAPK." (PMID 31781219, 2019). "This may be relevant given the finding that an IL1-b blocker was ineffective in treatment of chronic fatigue syndrome." (PMID 36217374, 2022). "Patients with chronic fatigue syndrome/myalgic encephalitis show increases in both IL-1β and IL-6." (PMID 26469939, 2015). "In patients with myalgic encephalomyelitis/chronic fatigue syndrome (ME/CFS), who manifests with fatigue, malaise, sleep disorders, and cognitive problems, the exosome-associated mtDNA could stimulate human microglia to release IL-1β." (PMID 37021129, 2023). "Some studies have suggested that a reduction in tissue inflammation may alleviate chronic fatigue, such as TNF-α, IL-1β, and IFN-γ play a major role in the development of chronic fatigue syndrome." (PMID 34063723, 2021).
chronic lung disease (9 papers, 2011 to 2024). According to the definitions of the American and British Thoracic Societies, including pulmonary functional tests, X-rays, and CT scans for items such as fibrosis, bronchiectasis, bullae, emphysema, nodular or lymphomatous abnormalities. "Specifically, in HIV-1 patients increased levels of circulating interleukin-6(IL-6), Tumour Necrosis Factor-α (TNF-α), interleukin-1 beta (IL-1β) and C-reactive protein have been associated with chronic lung disease." (PMID 32059509, 2020). "in the airways with lower levels of inflammatory markers (i.e. IL-8, IL-6 and IL-1β) in chronic lung diseases." (PMID 37168857, 2023). "We analyzed the expression of selected genes associated with AM plasticity (Ccl22, Ccl17, Mmp12, and Arg1) and inflammation in chronic lung diseases (Il1a and Il1b)." (PMID 34764283, 2021). "It is well known that the expression and secretion of MMP-9 in chronic lung diseases is regulated by various stimuli, including IL-1β, TNF-α, and LPSs." (PMID 32829707, 2020). "Thus, we propose that IL-36R blockade in patients with chronic lung disease prone to microbial exacerbations will alleviate symptoms while preserving sufficient innate immune signaling mediated by IL-1α and IL-1β to conserve host defense." (PMID 33558616, 2021). "Furthermore, published studies have suggested that the release of inflammatory cytokines involving IL-1β, IL-6, and TNF-α participated in activating p38 MAPK and JNK signaling pathways in chronic lung diseases." (PMID 35754478, 2022). "Nevertheless, pulmonary resistance in mice lacking IL-1β was significantly reduced already after LPS/elastase exposure alone, thus supporting the described role for IL-1β in the development of chronic lung disease." (PMID 24918427, 2014).
coccidiosis (9 papers, 2011 to 2024). A parasitic infection caused by Coccidia. "In coccidiosis, there is increased synthesis of proinflammatory cytokines such as IL-1β, IL-6, and TNF-α, which further disrupt the TJ barrier and amplify the inflammatory process by allowing more luminal antigens to permeate." (PMID 37763330, 2023). "In comparison to D3 at the same level of supplemental dietary inclusion, it has likewise been shown that the expression of IL-10 increased and IL-1β decreased in response to 2760 IU/kg of 25OHD3 in broilers challenged with coccidiosis." (PMID 36230268, 2022). "For caecal coccidiosis, elevated expression of IL-1β was previously reported during E. tenella infection." (PMID 21980402, 2011). "When both dietary (69 μg/kg feed) and in ovo (2.4 μg) sources of 25(OH)D3 were individually administered in normal or coccidiosis-infected poultry species, positive effects have been observed on the expressions of anti-inflammatory (IL-1β) and pro-inflammatory response (IL-10 and TGF-β4) genes." (PMID 39794953, 2024). "In addition, in vivo studies showed that QCC reduced blood stool in chickens with coccidiosis, restored cecal injury, and significantly reduced the mRNA and protein expression levels of IL-1β, IL-10, and IFN-γ in ceca (p < 0.01)." (PMID 38496310, 2024). "Generally, cytokines such as IL-1β, IL-12, IFN-γ, and TNF-α promote the development of cellular-mediated immunity against intracellular infections including coccidiosis." (PMID 38751432, 2024). "Generally, cytokines such as IL-12, IFN-γ, IL-1β and TNF-α promote the development of cellular mediated immunity against intracellular infections including coccidiosis." (PMID 21980402, 2011).
colon adenocarcinoma (9 papers, 2013 to 2025). "Upregulation of CLDN2 by TNFα was further confirmed in a human colonic adenocarcinoma cell line (Caco2) treated with TNFα (20 ng/mL) or IL-1β (10 ng/mL), respectively." (PMID 37287024, 2023). "Bearing in mind the increasing interest in low-grade inflammation and its role in the development of a wide range of inflammation-related disorders, we purposed to track the cytokines secretion in PMNs (TNF-α, IL-8, IL-1β) as well as in human colon adenocarcinoma cell line Caco-2 (IL-8)." (PMID 34834710, 2021). "Survival analysis on GEPIA using colon adenocarcinoma data set screened 5 genes CXCL3, IL1B, IL1A, MET and TNS1 that have significant log rank p value in Kaplan–Meier survival analysis." (PMID 34083590, 2021). "A recent study demonstrated that propionate, similarly to butyrate, may inhibit the activation of NF-κB in colon adenocarcinoma cell line with a consequent reduction of pro-inflammatory factors expression such as TNF-α and IL-1β in colon tissues." (PMID 32344758, 2020).
contact dermatitis (9 papers, 2014 to 2024). An inflammatory skin condition caused by direct contact between the skin and either an irritating substance or an allergen. "Cutaneous inflammation was evaluated with clinical scoring, ultrasound imaging, skin thickness, histology, and analyses of selected biomarkers for contact dermatitis, IL-1β, TNF-α, CXCL10, and CXCR3." (PMID 31875186, 2019). "RT-PCR analyses also revealed mRNA upregulation of pro-inflammatory cytokines (IL-1β and IL-6) and some Th1 or Th2 cytokines (IFNγ, IL-4, and IL-10), but not that of IL-2, TGFβ, and IL-17, at the delayed phase of oxazolone-induced contact dermatitis, similar within the three genotypes." (PMID 36768979, 2023). "Previous in vivo and in vitro studies demonstrated that haptens activate skin cells and induce the production of several cytokines including IL-1β that stimulates the migration of skin dendritic cells to the lymph nodes and has a key role in contact dermatitis." (PMID 24465826, 2014). "They found that CA has anti-inflammatory activities in both acute and chronic contact dermatitis models through blocking of mRNA and protein synthesis of the cytokines, such as TNF-α, IL-6, and IL-1β, and neutrophil-mediated myeloperoxidase activity." (PMID 34040528, 2021). "Corneocyte concentrations of the inflammasome‐mediated cytokines IL‐1β and IL‐18 in treated skin lesions (disulfiram 5%, mometasone 0.1% or vehicle) of SDS‐induced irritant contact dermatitis were assessed by tape stripping and ELISA 48 h after application of SDS." (PMID 34322217, 2021). "In a mouse model of irritant contact dermatitis induced by croton oil, topically applied recombinant human TRX significantly suppressed the inflammatory response by inhibiting the production of cytokines and chemokines, such as Tnf-α, Il-1β, Il-6, Cxcl1, and Mcp-1, in the skin tissues." (PMID 32244938, 2020).
disseminated candidiasis (9 papers, 2010 to 2021). Systemic candidiasis occurs when Candida yeast enters the bloodstream and may spread (becoming disseminated candidiasis) to other organs, including the central nervous system, kidneys, liver, bones, muscles, joints, spleen, or eyes. "Additionally, impaired control of pulmonary histoplasmosis and disseminated candidiasis was observed in Il1r1-deficient and Il1a/Il1b-doubly deficient mice, respectively." (PMID 25629406, 2015). "In the mouse model of disseminated candidiasis, candidalysin is dispensable for IL-1β production in the kidneys, but essential for IL-1β production in the brain." (PMID 33471869, 2021). "Both IL-1α and IL-1β have also been shown to play an important role in disseminated candidiasis, and IL-1 signaling has shown to contribute to host resistance against pulmonary histoplasmosis and Coccidioides sp." (PMID 29403476, 2017). "It is the neutrophils that form the backbone of the inflammatory infiltrates during disseminated candidiasis, and this explains the dependency of host defense against Candida on IL-1β, most likely activated by neutrophil-derived PR3, rather than caspase-1." (PMID 20195505, 2010). "For instance, host resistance to disseminated candidiasis is provided by neutrophil-derived proteinase 3 activation of IL-1β and not caspase-1 activation." (PMID 30583612, 2018).
Down syndrome (9 papers, 2012 to 2026). "Moreover, IL-1β upregulation has been reported before the establishment of an overt AD pathology in Down syndrome." (PMID 34218796, 2021). "The presence of excess IL-1β and ubiquitinated aggregates is early and pervasive events in what may be considered as Alzheimer pathogenesis in Down’s syndrome and as we propose, analoguously, in AD." (PMID 31882005, 2019).
enterocolitis (9 papers, 2017 to 2026). An inflammatory process affecting the small intestine and colon. "Meanwhile, it was reported that IBD patients have reduced levels of butyric acid in their feces, accompanied by elevated levels of IL-1β and TNF-α, suggesting that the mice in the high-dose group were at high risk of developing enterocolitis." (PMID 40565727, 2025).
food allergy (9 papers, 2020 to 2025). Gastrointestinal disturbances, skin eruptions, or shock due to allergic reactions to allergens in food. "S100A8/A9 and inflammatory-related factors, including TLR4, NF-κB, TNF-α, IL-6 and IL-1β, is closely related to food allergies." (PMID 33499808, 2021). "However, induction of a food allergy to OVA led to significant upregulation of Il17a along with elevated expression of Il1b and Il12a, indicating that allergic inflammation augments the inflammatory response to C. albicans in the glandular stomach." (PMID 39347572, 2024). "We have also previously reported that the non-T cell fraction from food allergic infants showed increased inflammatory cytokine responses (TNFα, IL-6, IL-1β, and IL-8) to LPS stimulation, and that this was more pronounced in infants with persistent food allergy outcomes." (PMID 33072108, 2020). "In cord blood, infants who developed food allergies showed a higher ratio of monocyte/CD4+ T cells, which would secrete higher amounts of inflammatory cytokines, such as IL-1β, IL-6, and TNF-α that further suppressed IL-2 expression by CD4+ T cells." (PMID 38263182, 2024). "In our study, we also observed significant decreases in DNAm levels for the gene IL1B and IL6 in PA compared with NA individuals, suggesting a link between epigenetic regulation of the innate immune system and food allergy." (PMID 33571165, 2021). "A study demonstrated that only the level of TNF-α was increasing in the cerebral cortex of food allergy mice; the levels of IL-1β and IL-6 were not changed." (PMID 40429903, 2025).
helminth infection (9 papers, 2013 to 2025). "Indeed in mice deficient for IL-1β (IL-1β−/−), or treated with the soluble IL-1βR antagonist, Anakinra, helminth infection results in enhanced type 2 immunity and accelerated parasite expulsion." (PMID 23935505, 2013). "In contrast, the downregulation of IL1B observed on day 3 probably results in IL-25 and IL-33 suppression, supporting chronic helminthic infection." (PMID 37600806, 2023). "In the current report we uncover a novel role for IL-1β production in promoting the chronicity of intestinal helminth infection." (PMID 23935505, 2013). "From precedents in other helminth infections, IL-1β (and IL-18) could contribute to local inflammation, downregulate Th2 responses, and/or promote Th1 and Th17 responses, both of which are detectable in cystic echinococcosis (28, 58, –, 60)." (PMID 32571988, 2020). "Our data clearly shows a role for IL-1β in attenuating protective type 2 immunity following Hp infection, however it will be necessary to study the role of this cytokine in modulating resistance against other species in order to gain a thorough picture of its exact role during helminth infection." (PMID 23935505, 2013). "To directly test the impact of helminth infection on TLR signaling, we collected the peritoneal macrophages from normal and helminth-infected mice and stimulated the cells with LPS (100 ng/ml) or IL-1β (1 ng/ml) for 6 h." (PMID 25010669, 2014). "Cytokine ELISA data showed that helminth infection significantly inhibited LPS-, but not IL-1β-, induced TNF-α and IL-6 production, suggesting that helminth infection specifically inhibits the TLR4 signaling pathway." (PMID 25010669, 2014). "Since the MyD88-mediated pathway plays a key role in IL-1R signaling, unimpaired IL-1β–induced TNF-α and IL-6 production by macrophages from helminth-infected host suggests that the effect of the helminth infection is not on MyD88-dependent signals, but is likely to be on the TRAM/TRIF pathway." (PMID 25010669, 2014).
Hydrocephalus (9 papers, 2021 to 2025). Hydrocephalus is an active distension of the ventricular system of the brain resulting from inadequate passage of CSF from its point of production within the cerebral ventricles to its point of absorption into the systemic circulation. "Inflammatory markers such as IL-6 and IL-1β are elevated during CNS inflammation and can activate the NF-κB pathway, which is currently the only demonstrated mechanism—besides malignancy—linked to choroidal CSF hypersecretion and hydrocephalus development." (PMID 40722587, 2025). "Hence, IL-1β also appears to have the prerequisites to promote choroidal CSF hypersecretion and cause hydrocephalus development." (PMID 33613789, 2021). "A systematic review discussed inflammatory markers’ changes in hydrocephalus and reported that IL-6, IL-1β, and LRG were most consistently elevated in CSF from iNPH patients, while other markers showed limited or no consistent changes." (PMID 40722587, 2025). "aSAH patients presented significantly higher levels of caspase-1, IL-18, and IL-1β in CSF for all timepoints when compared with hydrocephalus patient controls." (PMID 39195261, 2024). "A study has shown that neuroinflammation is found in ventricular dilation in rats with hydrocephalus and suggests that it is involved in the upregulation of IL-1β secreted by astrocytes in the early stages of the disease." (PMID 36226316, 2022). "Microglia are the main source of IL-1β, mainly expressed in astrocytes and perivascular macrophages 4 weeks after hydrocephalus induction." (PMID 36226316, 2022). "We identified six inflammatory markers, IL-6, IL-1β, LRG, IL-18, VEGF, and IFN- γ, which were associated with the most evidence of increased levels in CSF from patients with hydrocephalus compared to control subjects." (PMID 33613789, 2021). "Both DCX and GPC2 associated with hydrocephalus, NSE, IL-1β, IL-2, IL-8, IL-13." (PMID 36800341, 2023). "Hemorrhagic brain injury in the setting of GMH induces a substantial increase in the production of pro-inflammatory cytokines (IL-1β and IL-6) within the brain, which may consequently progress to hydrocephalus." (PMID 35720361, 2022). "Significant, positive associations were found for both CSF-DCX and CSF-GPC2 respectively, with hydrocephalus, NSE, IL-2, IL-8, IL-13, and IL-1β." (PMID 36800341, 2023). "Despite the heterogenous control group, we demonstrate that aSAH patients had significantly higher levels of ASC, caspase-1, IL-18, and IL-1β up to 5 days post-injury when compared to hydrocephalus non-aSAH patient controls." (PMID 39195261, 2024). "In a hydrocephalus mouse model, Nec‐1 and GSK872 reduce necrotic cell death, effectively inhibit the phosphorylation of RIP3 and MLKL, and reduce the levels of inflammatory factors such as IL‐1β, IL‐6 and TNF‐α in the cortex and hippocampus." (PMID 34374150, 2021). "IL-6, IL-1β, LRG, IL-18, VEGF, and IFN-γ are elevated in CSF from patients with hydrocephalus and may be involved in promotion of hydrocephalus development and progression." (PMID 33613789, 2021). "Furthermore, we assessed several proinflammatory cytokines, such as IL‐1β, IL‐6 and TNF‐α, by Western blotting, and the results showed that the expression levels of IL‐1β, IL‐6 and TNF‐α in the cortex and hippocampus were increased in the hydrocephalus group compared with the sham group at 28 days." (PMID 34374150, 2021).
Legionella infection (9 papers, 2014 to 2025). "Legionellosis is another infectious disease which involves various factors that are associated with IL-1β in AD." (PMID 25585621, 2015). "We observed that monocytes cultured in aa− media had reduced IL1A and IL1B expression after treatment with GM-CSF and Legionella infection." (PMID 40470942, 2025). "During Legionella infection, the production level of IL-1β was significantly reduced in the supernatant of transfected macrophages with siRNA against Lpg2936 compared to control-transfected macrophages." (PMID 32064256, 2019). "Five DEGs (hsc70, hsp70a, hsc71, il-1β and ikkalpha) were enriched in both influenza A and legionellosis pathways, which are closely related to the immune system." (PMID 29904092, 2018). "As expected, pro-IL-1β translation was robust in wild type macrophages that were pre-treated with poly(I∶C) or with HKY followed by Legionella infection." (PMID 25058342, 2014). "Indeed, miR-146a was induced in lung epithelial cells, both after paracrine IL-1β exposure or direct legionella infection." (PMID 28931863, 2017). "the GSEA results showed that CXCL8, IL1B and CCL2 affect Graft-versus-host disease, Legionellosis, Primary immunodeficiency, Primary bile acid biosynthesis, Protein export and Non-homologous end-joining signaling pathways." (PMID 38167125, 2024). "Nlrp3−/− or Casp1−/− BMDCs infected with T4SS+Legionella exhibited WT levels of cell death, indicating that while NLRP3 and caspase-1 drive IL-1β release, they are not required for DC death during Legionella infection." (PMID 40530878, 2025).